TNF (tumor necrosis factor)
Diseases named in the same sentence as TNF in open-access papers (continued):
Sharing a sentence is not in itself a finding about the gene and the disease.
ischemic stroke (continued). "Epimedium treatment significantly inhibited the expression of IL-1β, TNF-α, and IL-6 and enhanced the expression of IL-4, which suggests that Epimedium exerted its neuroprotective effects via regulating the expression of proinflammatory and anti-inflammatory cytokine following ischemic stroke." (PMID 36338345, 2022). "Additionally, furthermore, there is preliminary evidence that targeting TNF may become a therapeutic approach in ischemic stroke." (PMID 35432523, 2022). "Additionally, in a study about the relationship between ex vivo cytokine synthesis and 3-month outcomes after ischemic stroke, decreased release of IP-10, TNFα, IL-1β, and IL-12; increased release of IL-10 and IL-8; and higher plasma IL-6 levels were associated with poor outcomes." (PMID 36439158, 2022). "Moreover, IL-19 treatment can significantly reduce the up-regulation of TNF-α and IL-6 mRNA expression after ischemic stroke, inhibit the increase of microglia, macrophages, CD4+ T cells, CD8+ T cells, and B cells, and suppress the activation of macrophages and neutrophils." (PMID 35173738, 2022). "In the acute phase of ischemic stroke, resident microglia and recruited macrophages assume an M2 phenotype, and the immune-mediated inflammatory response is activated, resulting in the secretion of a number of inflammatory cytokines (IL-6, IL-1β, and TNF-α and the proteolytic enzymes MMP 3 and 9)." (PMID 34276353, 2021). "TNF, also known as TNF-alpha, is secreted mainly by macrophages and is capable of mediating certain tumor cell death, is an important inflammatory mediator after ischemic stroke, can affect the permeability of the blood-brain barrier, and is closely associated with neurotoxicity." (PMID 34603472, 2021). "Also, TNF inhibitors hold promise as candidate therapies in ischemic stroke." (PMID 32503645, 2020). "Finally, TNF, a pro-inflammatory cytokine synthesized by monocytes, macrophages, and Th1 lymphocytes, has been described as a predictive factor for the development of ischemic stroke in patients with chronic NVAF." (PMID 32793635, 2020). "Taken together, these findings indicate that CSO treatment inhibited TLR4-mediated microglial activation and TNF-α secretion, thereby inhibiting NF-κB-mediated A1 astrocyte activation and reducing C3d expression and secretion, ultimately alleviating neuronal damage induced by ischemic stroke injury." (PMID 32917229, 2020). "Interestingly, PI3Kδ inhibition has been found to have a positive anti-inflammatory effect in ischemic brains and it has been proposed that PI3Kδ inhibition could help treat ischemic strokes via a mechanism involving tumor necrosis factor-α (TNF-α)." (PMID 31443495, 2019). "Additionally, the induction of proinflammatory cytokines, such as interleukin-8, tumor necrosis factor-α and interleukin-6, may be more frequent in adults <50 years with a history of ischemic stroke." (PMID 27355475, 2016). "However, the role of TNF-α production in ischemic stroke still remains controversial." (PMID 24223607, 2013). "BDNF could provide protection of brain in ischemic stroke via decreasing local TNF-α." (PMID 21490702, 2010). "Furthermore, it is presently unknown whether IL-1β and TNF-α are expressed to the same extent by the same or different subsets of microglia and macrophages following ischemic stroke." (PMID 18947400, 2008). "For example, in a mouse model of ischemic stroke, microglia‐specific PGC‐1α overexpression suppresses NLRP3 inflammasome activation; reduces TNF‐α, IL‐1β, and IL‐6 production; enhances mitophagy; and significantly improves neurological outcomes." (PMID 41517974, 2026). "Certain subgroups of ischemic stroke patients had the lowest expression levels of SOD, BMAL1, and SIRT1, whereas other subgroups had the highest levels of MDA, IL-6, and TNF-α." (PMID 41567643, 2025). "TNF-α, TNF-β, IFN-γ, and IL-12 are markers, which are useful to distinguish ischemic stroke survivors from healthy controls." (PMID 40520895, 2025).
ischemic stroke (continued). "The concentration of salivary TNF-α, TNF-β, IFN-γ and IL-12 significantly distinguish patients with ischemic stroke from healthy individuals." (PMID 40520895, 2025). "ROC diagnostic utility analysis in our study indicates that salivary TNF-α, TNF-β, IFN-γ, and IL-12 levels significantly differentiate ischemic stroke patients from healthy individuals (AUC = 1, sensitivity = 100%, specificity = 100%)." (PMID 40520895, 2025). "In our study, the direct proportional correlation between IL-6, TNF-alpha, and NIHSS scores further emphasizes the role of these inflammatory markers in the early and late stages of ischemic stroke." (PMID 39859987, 2025). "For example, microglia-derived TNF-α has been reported to mediate endothelial necroptosis and exacerbate damage to the blood–brain barrier (BBB) following ischemic stroke." (PMID 40867580, 2025). "Our results showed higher MDA, IL-6, and TNF-α levels, and lower SOD, SIRT1, and BMAL1 levels in ischaemic stroke patients compared to control patients (P < 0.05)." (PMID 38245621, 2024). "Specifically, patients with ischemic stroke onset from subgroup 2 (6:00–11:59) exhibited significantly increased levels of MDA, IL-6, and TNF-α, and decreased activity of SOD." (PMID 38245621, 2024). "Following ischemic stroke, microglia/macrophage VDR-CKO mice exhibit an enhanced M1 phenotype in microglia/macrophages, with substantial secretion of TNF-α and IFN-γ." (PMID 39649720, 2024). "Pro-inflammatory cytokines, including IL1α, IL1β, IL6, TNFα, and the number of CD16 + and CD206 + microglia (especial CD16 + microglia), increased after ischemic stroke." (PMID 38287382, 2024). "We assessed neurological deficits, infarct volume, blood–brain barrier (BBB) permeability, TNF-alpha levels, total oxidant capacity, and gene expressions that play a role in BBB integrity (VEGF, Occludin, and MMP-9) following ischemic stroke." (PMID 39309404, 2024). "As the results showed, there was increased production of pro-inflammatory cytokines, including TNF-α, IL-6, and IL-1β, in the CMI+PT group compared to the PT group on the first day after ischemic stroke." (PMID 38216560, 2024). "To further investigate the relationship between NLRP1 and inflammatory factors in ischemic stroke patients, we measured the serum levels of NLRP1, CRP, IL-6, TNF-α, and IL-1β by ELISA." (PMID 37000063, 2023). "Taken together, IL-17A, TNF-α, and VEGF-A are closely related to ischemic stroke occurrence and development." (PMID 37287803, 2023). "In conclusion, we identified multiple candidate plasma protein biomarkers of 3-month outcome after ischemic stroke involved in, e.g., NLRP3 inflammasome regulation and signaling pathways, such as TNF, JAK/STAT, MAPK, and NF-κB." (PMID 37794467, 2023). "In ischemic stroke, MMP‐9 activates proinflammatory cytokines and chemokines, such as CXCL8, IL‐1β, and TNF‐α." (PMID 37452512, 2023). "As reported recently in a clinical study, NBP combination with Edaravone treatment significantly decreased serum Tumor necrosis factor-α (TNF- α), C-reactive protein (CRP), and Interleukin-6 (IL-6) levels of ischemic stroke patients." (PMID 37243759, 2023). "The NIHSS score, the mRS score after 90 days and the levels of NLRP1, CRP, TNF-α IL-6 and IL-1β of ischemic stroke patients in the ASITN/SIR grade 0 to 2 group were remarkably elevated than the ischemic stroke patients in ASITN/SIR grade 3 to 4 group." (PMID 37000063, 2023). "In MCAO rat models, miR-381-3p presents a low expression, but overexpression of miR-381-3p can hinder TNF-α signaling axis activation, facilitate EPC angiogenesis, and curb inflammation via silencing MapK38 or Cebpb, thus guarding against ischemic stroke." (PMID 35246016, 2022).
ischemic stroke (continued). "Our findings indicate that ischemic stroke leads to astrogliosis in the cerebral cortex, while AP-1 transcriptionally upregulates TNF-α, and that TNF-α released by activated astrocytes induces high platelet reactivity through the RIP1/RIP3/AKT pathway." (PMID 35781632, 2022). "Nevertheless, polyphenols exhibited anti-inflammatory properties in obese mice after ischemic stroke, by reducing the elevation of pro-inflammatory markers in the brain including IL-1β, IL-6, MCP-1 and TNF-α." (PMID 35624723, 2022). "Published studies have paid little attention to the correlations between Lp-PLA2 activity (or mass) and other ischemic stroke biomarkers, including CRP, MMPs, IL-6, TNF-α, VCAM1, ICAM1, S100B, vWF, BNGF, and MCP1." (PMID 36313479, 2022). "The network pharmacology results demonstrated that the potential targets of SHD against ischaemic stroke were significantly enriched in the PI3K-Akt and TNF pathways." (PMID 34985385, 2022). "In RT-PCR assays, mRNA levels of TNF-α, IL-1β, MMP-2, and MMP-9 were remarkably elevated following ischemic stroke." (PMID 36186136, 2022). "In addition, the neutralization of TNF-α is an effective therapeutic strategy against ischemic stroke that may be used as a potentially novel mechanism to provide protection for platelets during ischemic stroke." (PMID 35781632, 2022). "In this study, we found “TNF signaling pathway” and “NOD-like receptor signaling pathway,” the two signaling pathways are both significantly enriched in the ischemic stroke and celastrol post-treatment process." (PMID 35677353, 2022). "Earlier studies have shown that after ischemic stroke, Zileuton suppresses NF-κB activation and the levels of inflammatory cytokines were decreased (LTB4, TNF-α, IL-6, IL-1β)." (PMID 33878031, 2021). "RO27-3225, a melanocortin MC4 receptor agonist, reduces the expression of TNF-α, Bax, ERK, JNK, and caspase-3 and promotes improved functional recovery following ischemic stroke in gerbils." (PMID 35008440, 2021). "In different types of models, such as ischemic stroke, GPER1 on microglia was also suggested to mediate the effect of decreasing IL-1β and TNF-α under G1 or estradiol stimulation." (PMID 34239558, 2021). "In an ischemic stroke mouse model, ORM inhibited the production of the inflammatory cytokines IL-1β, IL-6, and TNF-α." (PMID 33013889, 2020). "In response to inflammatory mediators (e.g., tumor necrosis factor-α, interferon-γ), neutrophils and macrophages produce CXCL-1, which exerts neutrophil-chemoattractant activity during the early phase of ischemic stroke." (PMID 31083528, 2019). "Tumor necrosis factor (TNF) is a multifunctional, proinflammatory cytokine that participates in all phases of ischemic stroke, from development to repair and long-term inflammatory effects." (PMID 31440125, 2019). "Our report shows that SLI treatment prevent brain injury after ischemic stroke by decreasing the expression of RAGE, MMP9 and inflammatory factors (COX-2, TNF-α and ICAM-1) in T1DM + MCAO rats." (PMID 28486941, 2017). "The cytokines that modulate tissue injury in ischemic stroke, TBI, spinal cord injury (SCI), or heatstroke, including tumor necrosis factor‐α (TNF‐α), interleukin (IL)‐1, and IL‐6, are potential targets for future therapy." (PMID 27781140, 2016). "Brazilein is an important pro-inflammatory cytokines inhibitor, it has been demonstrated a neuroprotective effect though suppress TNFα and IL6 mRNA expressions, the treatment prospects on ischemic stroke have been widely reported." (PMID 27672514, 2016). "IL-1β and TNF-α, the major YKL-40 inducer cytokines, are synthesized from microglia and macrophages in penumbra after ischemic stroke." (PMID 23272150, 2012). "Interleukin-1β (IL-1β) and tumor necrosis factor-α (TNF-α) are expressed by microglia and infiltrating macrophages following ischemic stroke." (PMID 18947400, 2008).
ischemic stroke (continued). "Previous studies have demonstrated that newly repopulated microglia had reduced expression of inflammatory markers (e.g., IL-1β, IL-6, TNF-α and CD86), and upregulation of neuroprotective factors (e.g., CD206, TGF-β, and IL-10) in response to ICH ischemic stroke in ageing." (PMID 40777042, 2025). "We found significantly higher levels of salivary pro-inflammatory cytokines (IL-1β, TNF-α, TNF-β), anti-inflammatory cytokines (IL-1ra, TRAIL), Th1 cytokines (IFN-γ and IL-12 (p40)), and Th2 cytokines (IL-6) in patients with ischemic stroke compared to healthy participants." (PMID 40520895, 2025). "The absence of ADAMTS13 in mice with ischemic stroke has been correlated with increased myeloperoxidase activity and expression of pro-inflammatory cytokines such as interleukin-6 and tumor necrosis factor-α." (PMID 40217918, 2025). "Among the four subgroups, the content of MDA, IL-6, and TNF-α was highest in patients with ischaemic stroke onset from subgroup 2 (06:00–11:59), while the expression levels of SOD, BMAL1, and SIRT1 were lowest in patients with ischaemic stroke in subgroup 2." (PMID 38245621, 2024). "In the Nor-COAST study (Norwegian Cognitive Impairment After Stroke), levels of serum ILs, terminal C5b-9 complement complex (TCC), TNF, monocyte chemoattractant protein (MCP-1), and macrophage inflammatory protein (MIP) were measured at baseline, 3, and 18 months after ischemic stroke." (PMID 41542283, 2024). "When an ischemic stroke occurs, the lack of α9 in neutrophils limits the inflammatory response by lowering TNF-α, IL-1β, and IL-6 levels." (PMID 39649720, 2024). "After ischemic stroke, TREM2-KO mice exhibit reduced microglial activity, with decreased transcription of pro-inflammatory cytokines TNFα, IL-1α, and IL-1β, as well as reduced transcription of chemokines CCL2 (MCP1), CCL3 (MIP1α), and chemokine receptor CX3CR1." (PMID 39649720, 2024). "Tumor necrosis factor (TNF)-α-stimulated gene 6 (TSG-6), a hyaluronate (HA)-binding protein, has recently been involved in the regulation of the neuroimmune response following ischemic stroke." (PMID 39329947, 2024). "Cyclooxygenase inhibition can eliminate TNF-α-, IL-1β-, and IL-6-induced increase in endothelial paracellular permeability, suggesting a role for arachidonic acid in increasing BBB permeability during ischemic stroke." (PMID 37840921, 2023). "When exposed to pro-inflammatory molecules, such as the tumor necrosis factor (TNF; aliases are TNFSF2, TNFA, and TNFα), injury, or ischemic stroke, astrocytes acquire a reactive phenotype, suffering dramatic morphological changes and overexpressing specific proteins." (PMID 36895046, 2023). "Notably, the infarct volume, neurological deficits, immune infiltrates, and pro-inflammatory molecules (IL-1β, TNF-α, CCL2, and CXCL1) were attenuated in LCN2–/– mice after ischemic stroke." (PMID 36187347, 2022). "Extensive research has shown that PTX could reduce the secretion of inflammatory cytokines such as tumor necrosis factor-α (TNF-α), interleukin-1β (IL-1β), IL-6, IL-8 by inhibiting microglia/macrophage activation in neuropathic pain and ischemic stroke models." (PMID 35642056, 2022). "Moreover, it is also reported to suppress inflammation (even the production of TNFα and IL6) and is involved in the protection of the brain from the deleterious effects of ischemic stroke." (PMID 36572898, 2022). "According to the results of pathway enrichment, SHD may act against ischaemic stroke via the PI3K-Akt, TNF and HIF-1 pathways, among others." (PMID 34985385, 2022). "The enrichment results demonstrated that the “MAPK signalling pathway,” “Toll-like receptor signalling pathway,” “Prolactin signalling pathway,” “TNF signalling pathway,” “ErbB signalling pathway,” and “HIF-1 signalling pathway” were closely related to the onset and progression of ischaemic stroke." (PMID 35815278, 2022).
ischemic stroke (continued). "In addition, inhibition of TNF-α, a strong pro-inflammatory cytokine that increases neuronal death and BBB damage, exhibit neuroprotective effect in rodent models of ischemic stroke." (PMID 36313349, 2022). "Additionally, GSVA showed oligodendrocyte subcluster 9 was enriched in IL-6, complement, TNF-α pathway, and Kras signaling, suggesting that Sgk3 from oligodendrocytes may play an important role regulating oligodendrocyte viability and inflammatory responses during the acute stage of ischemic stroke." (PMID 33692998, 2021). "Inflammatory M1 microglia secret inflammatory factors such as TNF-α, iNOS and CCL2 to promote inflammatory processes, which may aggravate autologous brain damage in the early stage of ischemic stroke." (PMID 33532127, 2021). "Some studies, however, reported on increased blood TNF levels sampled within 12 h, 24 h, or 72 h after symptom onset in ischemic stroke patients compared to healthy controls, though not in patients with lacunar stroke." (PMID 32503645, 2020). "Additionally, we measured blood TNF, TNFR, and IL-1 levels in surviving ischemic stroke patients within the first 8 h and again at 72 h after symptom onset and compared levels to healthy controls." (PMID 32503645, 2020). "A KEGG enrichment analysis of the candidate targets in this PPI network disclosed 10 ischemic stroke-related signaling pathways, namely, HIF-1, FoxO, adherens junction, NF-kappa B, PI3K-Akt, TGF-beta, NOD-like receptor, Hippo, apoptosis, and TNF (ordered in P value)." (PMID 32908557, 2020). "Both TNF-α and IL-1 primarily produced by microglia/macrophages are overexpressed within the first 2 h after experimental ICH and as early as 24 h after ischemic stroke in mice." (PMID 32733433, 2020). "In addition, we compared blood levels of IL-1α, IL-1β, IL-1Ra, TNF, TNFR1, and TNFR2 in samples from ischemic stroke survivors and healthy controls." (PMID 32503645, 2020). "The MCAO challenge itself induced a significant up-regulation of pro- and anti-inflammatory genes in the brains of both control and treatment animals, including IL-6, IL-1β, TNF-α, IL-10, CCL2, and CCL3, indicating a pivotal role of neuroinflammation in the pathology of acute ischemic stroke events." (PMID 30126083, 2018). "Importantly, although it has been demonstrated that, following the onset of ischemic stroke, the expression of TNF-α in the peripheral circulation and central nervous system increases, the effect of TNF-α in the ischemic brain is as of yet unclear." (PMID 22394384, 2012). "TNF-α effects on lipid metabolism, coagulation, and endothelial function, and the increasing release of TNF-α may contribute to the odds of ischemic stroke patients." (PMID 23050663, 2012). "We have shown for the first time that IL-1β and TNF-α are produced by largely non-overlapping subsets of microglia and macrophages after induction of ischemic stroke in mice." (PMID 18947400, 2008). "Since TNF-α is an immunomodulatory cytokine involved in neuroinflammation and neuronal damage in response to ischemia, thus the use of TNF-α inhibitors could be beneficial in the treatment of ischemic stroke." (PMID 40364646, 2026). "Moreover, ischemic stroke patients have higher levels of oxidative stress and inflammatory markers, such as IL-6, TNF-α, MDA, and SOD, than non-stroke patients." (PMID 41567643, 2025). "Considering that TNF, SPP1, MIF, and GALECTIN signaling pathways are involved in various forms of programed cell death (PCD), we hypothesized that PANoptosis contributes critically to ischemic stroke pathology." (PMID 41235394, 2025). "Studies demonstrate that the Sirt1-Bmal1 pathway also plays a crucial role in ischemic stroke, exerting regulatory effects in the early stages by modulating the expression of oxidative stress and inflammatory markers such as MDA, SOD, IL-6, and Tumor Necrosis Factor-alpha." (PMID 40527853, 2025).